TSHR (thyroid stimulating hormone receptor)
Description:
Receptor for the thyroid-stimulating hormone (TSH) or thyrotropin. Also acts as a receptor for the heterodimeric glycoprotein hormone (GPHA2:GPHB5) or thyrostimulin. TSHR is coupled to G(s) proteins and mediates the activation of adenylate cyclase. This leads to the generation of cyclic adenosine monophosphate (cAMP), which in turn activates protein kinase A (PKA). PKA subsequently phosphorylates downstream targets involved in thyroid hormone biosynthesis and secretion, including thyroid peroxidase (TPO) and the sodium/iodide symporter (NIS). Additionally, plays a central role in controlling thyroid cell metabolism (By similarity).
Synonyms: LGR3; CHNG1; hTSHR-I
Tractability: Small molecule: a structure with a bound ligand is known; it belongs to a druggable protein family. Antibody: UniProt places it where antibodies can reach, with high confidence; its Gene Ontology location is reachable by antibodies, with high confidence; UniProt predicts a signal peptide or a membrane-spanning region. PROTAC: ubiquitination databases record sites on it; a small molecule that binds it is known. Other modalities: an approved drug acts on it.
Target class: Membrane receptor; Family A G protein-coupled receptor; Peptide receptor (family A GPCR); Glycohormone receptor
Chemical probes: ML109, ML224
Gene: Protein-coding gene on chromosome 14 (80,954,989 to 81,146,306, forward strand). Ensembl gene ENSG00000165409.
Subcellular location: Cell membrane; Basolateral cell membrane
Pathways (Reactome):
Signal Transduction: G alpha (s) signalling events; Hormone ligand-binding receptors
Gene Ontology:
Molecular function: G protein-coupled receptor activity; protein binding; protein-containing complex binding; signaling receptor activity; thyroid-stimulating hormone receptor activity; G protein-coupled peptide receptor activity; protein-hormone receptor activity
Biological process: adenylate cyclase-activating G protein-coupled receptor signaling pathway; cell surface receptor signaling pathway; cellular response to glycoprotein; cellular response to thyrotropin-releasing hormone; thyroid-stimulating hormone signaling pathway; cell-cell signaling; G protein-coupled receptor signaling pathway; G protein-coupled receptor signaling pathway, coupled to cyclic nucleotide second messenger; hormone-mediated signaling pathway; positive regulation of cell population proliferation; positive regulation of cold-induced thermogenesis; response to hormone
Cellular component: basolateral plasma membrane; plasma membrane; receptor complex; cell surface; membrane
Genetic constraint (gnomAD): Loss-of-function variants: 49 observed, 61.44 expected, observed/expected ratio (o/e) 0.8, 90% interval 0.63 to 1.01. The upper end of that interval is the gene's LOEUF score, 1.01, which puts it in group 4 of 6, group 1 being the genes least tolerant of losing a copy. Missense variants: 857 observed, 969.84 expected, observed/expected ratio (o/e) 0.88, 90% interval 0.83 to 0.94. Synonymous variants: 357 observed, 375.41 expected, observed/expected ratio (o/e) 0.95, 90% interval 0.87 to 1.04.
Homologues: Orthologues: chimpanzee TSHR (99% identical), macaque TSHR (97% identical), pig TSHR (90% identical), dog TSHR (89% identical), rabbit TSHR (89% identical), mouse Tshr (87% identical), rat Tshr (86% identical), guinea pig TSHR (85% identical), tropical clawed frog tshr (65% identical), zebrafish tshr (58% identical), Drosophila melanogaster Lgr1 (35% identical), Caenorhabditis elegans fshr-1 (27% identical). Paralogues in human: LHCGR (47% identical), FSHR (44% identical).
Diseases named in the same sentence as TSHR in open-access papers:
TSHR is named in the same sentence as 213 diseases in open-access papers, as found by Europe PMC text mining. Sharing a sentence is not in itself a finding about the gene and the disease. The quoted sentences say what the papers report.
Graves disease (453 papers, 2005 to 2026). Graves' disease is an autoimmune disorder that leads to overactivity of the thyroid gland (hyperthyroidism).It is caused by an abnormal immune system response that causes the thyroid gland to produce too much thyroid hormones. "Graves' disease is an autoimmune disease caused by autoantibodies to the thyroid-stimulating hormone receptor, which usually leads to hyperthyroidism in these patients." (PMID 41730272, 2026). "Graves’ disease is an organ-specific autoimmune disorder in which pathogenic immunoglobulins stimulate the thyroid-stimulating hormone receptor (TSH-R), causing thyroid follicular hyperplasia and excess thyroid hormone production." (PMID 41551367, 2026). "Graves’ Disease (GD), the most common form of hyperthyroidism in iodine-sufficient countries, is an autoimmune disorder characterised by thyroid-stimulating hormone receptor (TSH) autoantibodies causing overproduction of thyroid hormones." (PMID 41216059, 2025). "Graves’ disease (GD) is caused by stimulating antibodies that target the thyroid-stimulating hormone receptor (TSHR), referred to as TSH receptor antibodies (TRAb)." (PMID 40260258, 2025). "Graves’ disease is an autoimmune disorder in which the immune system attacks the thyroid gland, causing aberrant production of thyroid-stimulating hormone receptor antibodies (TRAb)." (PMID 41010493, 2025). "Graves’ disease is an inflammatory autoimmune state caused by thyrotropin (TSH) receptor autoantibody (TSHR-Ab)." (PMID 39941318, 2025). "Graves' disease is an autoimmune thyroid disorder characterized by the production of thyroid-stimulating hormone receptor antibodies and is one of the leading causes of hyperthyroidism." (PMID 40575205, 2025). "Thyroid-stimulating hormone receptor antibodies (TRAb) are the main pathogenic factors in Graves’ disease." (PMID 41157173, 2025). "In Graves’ disease, the loss of immune tolerance leads to immune-mediated infiltration of T lymphocytes and activation of TSH receptor (TSHR)-reactive B cells." (PMID 39872521, 2024). "Unexpectedly, thyroid-stimulating hormone receptor antibody (TR-Ab), a hallmark for thyrotoxicosis and assisting in the diagnosis of Graves’ disease, emerged as an independent predictor according to our results." (PMID 39363900, 2024). "Graves’ disease (GD) is the most common cause of hyperthyroidism mediated by autoantibodies against the TSH receptor (TSHR) and the insulin-like growth factor 1 receptor (IGF-1R)." (PMID 39685806, 2024). "Graves’ disease (GD) is an autoimmune disorder caused by autoantibodies against the thyroid stimulating hormone receptor (TSHR) leading to overstimulation of the thyroid gland." (PMID 37435490, 2023). "Graves’ disease is caused by a breakdown of immunological tolerance and the subsequent formation of antibodies that target the TSHR." (PMID 36830848, 2023). "Graves’ disease (GD) is an organ-specific autoimmune disease characterized by loss of T lymphocyte tolerance to self-antigens, most often to the thyroid-stimulating hormone receptor (TSHR)." (PMID 38202079, 2023). "Graves’ disease is an autoimmune disorder caused by auto-antibodies against the thyroid stimulating hormone receptor (TSHR)." (PMID 37810891, 2023). "Graves’ disease (GD) is caused by an autoimmune formation of autoantibodies and autoreactive T-cells against the thyroid stimulating hormone receptor (TSHR)." (PMID 37082124, 2023). "Graves’ orbitopathy (GO) can occur in patients with Graves’ disease due to pathogenic activation of TSHR in retro orbital fibroblasts." (PMID 38111381, 2023). "Graves’ disease (GD) is caused by the production of TSH-receptor (TSHR) stimulating auto-antibodies." (PMID 38107298, 2023). "Graves’ disease (GD) is an autoimmune disorder that is caused by autoantibodies against the thyroid stimulating hormone receptor (TSHR)." (PMID 37082124, 2023).
Graves disease (continued). "Graves' disease is a self-limiting autoimmune thyroid disorder caused by stimulating antibodies to the thyroid-stimulating hormone receptor." (PMID 37885564, 2023). "Polymorphisms of TSHR in enhancer regions, especially rs4411444 and rs4903961, are known to be associated with autoimmune diseases such as Graves’ disease and Hashimoto’s disease." (PMID 35053465, 2022). "Polymorphisms of TSHR have been shown to affect the development of central tolerance, thus explaining the occurrence of autoimmune phenomena such as Graves’ disease." (PMID 35053465, 2022). "(GPCR)The receptor for TSH receptor (TSHR), a G protein coupled receptor (GPCR), is of particular interest as the primary antigen in autoimmune hyperthyroidism (Graves’ disease) caused by stimulating TSHR antibodies." (PMID 36305581, 2022). "Incidentally, B cells are essential for the development of Graves’ disease in which hyperthyroidism is directly caused by thyroid stimulating antibodies that target the TSHR." (PMID 35572553, 2022). "Graves’ disease is the most common cause of hyperthyroidism, resulting from endogenous autoantibodies in the TSHR that overactivate the receptor, thereby stimulating TH synthesis and secretion as well as a diffuse goiter." (PMID 34440752, 2021). "Patients with activating TSHR variants demonstrated the same classical signs and symptoms of hyperthyroidism as seen in patients with Graves' disease." (PMID 33669123, 2021). "Graves’ disease (GD) is an antibody-mediated autoimmune disease associated with thyroid-stimulating hormone receptor (TSHR) in the thyroid gland that causes hyperthyroidism." (PMID 34051850, 2021). "Classical use of TSHr-Ab assay is in Graves’ disease where they are tested for diagnostic and prognostic issues; however, they can be used in specific settings of chronic autoimmune thyroiditis (CAT) as well." (PMID 34803929, 2021). "Thyroid-stimulating hormone receptor gene (TSHR), a gene encoding TSHR, is a major controller of thyroid cell metabolism, and its gain of function mutation leads to non-autoimmune hyperthyroidism (NAH), a condition of a prolonged state of hyperthyroidism." (PMID 34357084, 2021). "Graves’ disease (GD) is an autoimmune condition in which autoantibodies to the thyrotropin receptor (TSHR) cause hyperthyroidism." (PMID 33593429, 2021). "Graves' disease (GD) represents an autoimmune process in which circulating autoantibodies directed against thyrotropin receptor (TSHR)—TRAb (TSHR antibodies)—activate the thyroid gland, causing hyperthyroidism." (PMID 33776579, 2021). "The stimulation of the TSHR by TSHR-aAb is the underlying cause of Graves’ disease (GD), and associated with risk of Graves’ ophthalmopathy (GO)." (PMID 31940750, 2020). "As the direct cause of hyperthyroidism in Graves’ disease is stimulation of the TSHR, several groups have been developing approaches that directly prevent TSHR signaling, either through small molecules or by using antibodies that block receptor activation." (PMID 32845332, 2020). "TSHR antibody titre is considered a marker of severity of Graves' disease, with higher titres at diagnosis being associated with a longer time to achieve euthyroid status." (PMID 32477269, 2020). "Graves’ disease (GD) is an autoimmune disorder associated with the production of activating autoantibodies to the thyroid-stimulating hormone receptor (TSH-R) in the thyroid gland, leading to hyperthyroidism." (PMID 33414766, 2020). "Such small-molecule antagonists of TSHR attract much attention from scientists who are dedicated to developing new treatments for Graves’ disease, a pathological condition caused by binding of stimulatory autoantibodies to TSHR to induce hyperthyroidism." (PMID 32698392, 2020). "Graves’ disease (GD) is an autoimmune disease caused by autoantibodies (aAb) binding to and activating the thyroid-stimulating hormone receptor (TSHR)." (PMID 31721133, 2020).
Graves disease (continued). "Graves' disease (GD) is the most common cause of hyperthyroidism, and results from the production of autoantibodies that stimulate the cell-surface thyrotropin receptor (TSHR)." (PMID 31194638, 2019). "This study was designed to explore the association between Graves disease (GD) and thyroid-stimulating hormone receptor (TSHR) and cytotoxic T-lymphocyte-associated antigen 4 (CTLA-4) single nucleotide polymorphisms (SNPs)." (PMID 31565653, 2019). "Graves’ disease (GD) is an autoantibody-induced immune disorder related to the thyroid-stimulating hormone receptor (TSHR) in the thyroid gland, causing toxic goiter or hyperthyroidism." (PMID 31399042, 2019). "It is suggested that this truncated highly N-glycosylated α subunit contributes to Graves’ disease pathology in genetically susceptible patients via induction and/or maturation of the stimulating anti-TSHR." (PMID 30227620, 2018). "Graves’ Hyperthyroidism (GH) is an autoimmune condition caused by antibodies stimulating the thyroid stimulating hormone receptor (TSHR)." (PMID 29507751, 2018). "Graves’ disease (GD) is an autoimmune thytoid disorder that is caused by antibodies directed against the TSH-receptor (TSHR) leading to hyperthyroidism." (PMID 30166557, 2018). "In Graves’ disease (GD), autoantibodies to the thyrotropin receptor (TSHR) cause autoimmune hyperthyroidism." (PMID 29801507, 2018). "This difference likely reflects the importance of T cell immunity in EAE/MS versus autoantibodies in thyroid autoimmunity, particularly Graves’ disease for which stimulatory autoantibodies to the TSHR are the direct cause." (PMID 29326719, 2017). "Changes are rare in the epitopes recognized by TSHR antibodies, namely thyroid-stimulating antibodies (TSAbs), which are responsible for hyperthyroidism in Graves’ disease, and TSH-blocking antibodies (TBAbs), which cause hypothyroidism." (PMID 29326719, 2017). "Production of thyroid-stimulating hormone receptor (TSHR) antibodies represents the hallmark of Graves’ disease (GD) pathogenesis." (PMID 28421036, 2017). "Graves’ disease (GD) is a common organ-specific autoimmune disorder characterized by autoantibodies activating the thyrotropin receptor (TSHR) causing a hyperfunction of thyroid gland." (PMID 28521825, 2017). "Turning to responses to the TSHR, stimulating TSHR autoantibodies are the direct cause of hyperthyroidism in Graves’ disease [reviewed in Ref." (PMID 29326719, 2017). "Autoantibodies that arise spontaneously to the TSHR, the direct cause of Graves’ disease, have a number of unusual properties." (PMID 28620373, 2017). "Graves’ hyperthyroidism is caused by autoantibodies directed against the thyroid-stimulating hormone receptor (TSHR) that mimic the action of TSH." (PMID 27895620, 2016). "Thyroid-stimulating hormone (TSH) receptor (TSHR) autoantibodies (TRAbs) are the pathogenic hallmark of Graves’ disease." (PMID 27504107, 2016). "The stimulation of autoantibodies to TSHR (TRAbs) is known to be associated with hyperthyroidism in Graves’ disease (GD), and measurement of TRAbs is important for diagnosis of GD." (PMID 23852019, 2013). "As first reported by Hammar, thymic hyperplasia is commonly observed in Graves' disease, and homozygotes for an SNP allele predisposing to Graves' disease have significantly lower intrathymic TSHR transcripts than carriers of the protective allele." (PMID 24137108, 2013). "Graves disease (GD) is an autoimmune disease caused by self-reactive plasma cells which produce antibodies to the thyrotropin receptor that stimulate thyroid-stimulating hormone receptors and increase the production of thyroid hormone." (PMID 22824515, 2012). "To date, the only thyroid-related genes associated with AITD are TG (the gene encoding thyroglobulin), in both Graves' disease and Hashimoto's thyroiditis, and TSHR (the gene encoding the thyrotropin receptor) restricted to Graves' disease." (PMID 22530160, 2012).
Graves disease (continued). "Autoimmune hyperthyroidism, Graves' disease, can be induced by immunizing susceptible strains of mice with adenovirus encoding the human thyrotropin receptor (TSHR) or its A-subunit." (PMID 21738647, 2011). "Graves’ disease (GD) is an autoimmune disorder in which antibodies activate the thyrotropin receptor (TSHR) causing a hyperfunction of the thyroid gland." (PMID 22654555, 2011). "For example, activating mutations of the thyroid stimulating hormone receptor (TSHR) are found in some thyroid carcinomas and approximately 80% of thyroid adenomas, while germline mutations in TSHR cause familial non-autoimmune hyperthyroidism." (PMID 21853033, 2011). "Constitutively activating mutations in the TSHR are a frequent molecular cause of non-autoimmune hyperthyroidism." (PMID 21835055, 2011). "Even BALB/c mice, the most susceptible to developing hyperthyroidism in our induced Graves' disease model, develop high levels of TSHR-ELISA antibodies as well as functional TSHR antibodies (for example)." (PMID 21738647, 2011). "Constitutively activating germline mutations in the thyrotropin receptor (TSHR) gene result in non-autoimmune hyperthyroidism and can be transmitted as a dominant trait or occur sporadically." (PMID 21835055, 2011). "TED is closely associated with Graves' disease (GD), a common autoimmune disorder in which stimulatory autoantibodies against the thyroid-stimulating hormone receptor (TSH-R) cause the thyroid to produce excess thyroid hormone." (PMID 18354731, 2008). "Moreover, TSHR is one of the key targets for the correction of diseases caused by aberrant TSHR function (such as Grave’s hyperthyroidism, non-autoimmune hyperthyroidism, and thyroid cancer)." (PMID 40076260, 2025). "The development of allosteric inverse agonists and neutral antagonists for TSHR is necessary for the treatment of autoimmune hyperthyroidism (Graves’ disease) and associated ophthalmopathy, as well as for the treatment of thyroid cancer caused by activating mutations in TSHR." (PMID 37047169, 2023). "Graves disease (GD) affects 0.2% to 1.3% of the global population and is the most common cause of hyperthyroidism and the result of autoantibodies (TRAbs) to the thyrotropin receptor (TSHR)." (PMID 36683389, 2023). "Thyroid eye disease (TED) is the most common extra thyroidal manifestation of the autoimmune condition Graves’ disease (GD), which is caused by autoantibodies against the thyroid stimulating hormone receptor (TSHR) leading to overstimulation of the thyroid gland." (PMID 37435490, 2023). "Gut bacteria can influence host immune responses but little is known about their role in tolerance-loss mechanisms in Graves disease (GD; hyperthyroidism caused by autoantibodies, TRAb, to the thyrotropin receptor, TSHR) and its progression to Graves orbitopathy (GO)." (PMID 36683389, 2023). "The most common cause of hyperthyroidism is Graves’ disease (autoimmune hyperthyroidism), which is caused by autoantibodies to the thyroid-stimulating hormone receptor (TSHR) that acts as agonists and induce excessive thyroid hormone secretion, releasing the thyroid gland from pituitary control." (PMID 37697335, 2023). "TSHR mutations are also reported to be associated with Graves’ disease." (PMID 37686882, 2023). "Graves’ disease (GD) is an autoimmune condition of the thyroid caused by the excessive production of stimulatory antibodies (thyroid-stimulating antibodies, TSAb) against the thyroid-stimulating- hormone receptor (TSH-R)." (PMID 37152963, 2023). "TSH receptor (TSHR) antibodies are the cause of Graves’ disease and may also be found in patients with Hashimoto’s thyroiditis." (PMID 35909553, 2022). "As Graves’ disease is due to loss of tolerance to TSH receptor (TSHR), GO may be triggered by autoimmune reactions against TSHR, as supported by experimental and clinical evidence." (PMID 35604323, 2022).